TMEM217B (transmembrane protein 217B)
Gene: Protein-coding gene on chromosome 6 (37,212,181 to 37,258,144, reverse strand). Ensembl gene ENSG00000286105.
Subcellular location: Membrane
Gene Ontology:
Cellular component: membrane
Genetic constraint (gnomAD): Missense variants: 26 observed, 25.5 expected, observed/expected ratio (o/e) 1.02, 90% interval 0.75 to 1.41. Synonymous variants: 3 observed, 9.12 expected, observed/expected ratio (o/e) 0.33, 90% interval 0.15 to 0.85.
Homologues: Orthologues: dog TMEM217B (58% identical), rabbit TMEM217B (55% identical), rat Tmem217b (54% identical), mouse Tmem217b (53% identical), pig TMEM217B (51% identical). Paralogues in human: TMEM217 (25% identical).